IL1RL1 (interleukin 1 receptor like 1)
Diseases named in the same sentence as IL1RL1 in open-access papers (continued):
Sharing a sentence is not in itself a finding about the gene and the disease.
asthma (continued). "Interestingly, genome-wide association studies of asthma have identified RORα (a critical transcription factor for ILC2 development), as well as TSLP, IL-33 and the IL33-receptor (IL1RL1, ST2) as asthma susceptibility genes, supporting the importance of this pathway for asthma." (PMID 31024538, 2019). "Overall, our study suggests asthma patients carrying the extracellular and TIR domain risk haplotype and have a lung microenvironment that promotes elevated levels of cleaved IL33, particularly where IL3395–270 and IL33106–270 may be more amenable to IL33/IL1RL1 targeting." (PMID 39301832, 2024). "Asthma and AR share eight common genes (CLC, EMR4P, IL5RA, FRRS1, HRH4, SLC29A1, SIGLEC8, IL1RL1) that are presumed to describe the link for multimorbidity." (PMID 36825519, 2023). "Expression levels of IL1RL1 (P = 0.0002 vs. MA, P = <0.0001 vs. SA) and STAT6 (P = 0.0079 vs. MA, P = <0.0001 vs. SA) were significantly higher in mild-moderate and severe asthma compared to controls." (PMID 35386986, 2021). "Predictive interaction analysis revealed strong physical interactions between IL1RL1 and TMED1 which is unsurprising as both are related to IL33 signaling which has been extensively researched in the context of asthma." (PMID 35386986, 2021). "Interleukin 1 receptor like 1 (IL1RL1, ST2 ) is an important asthma gene and part of a cytokine receptor gene cluster." (PMID 33133517, 2020). "This previous study identified genes on chromosomes 2 (IL1RL1/IL18R1), 6 (HLA-DQ), 9 (IL33), 15 (SMAD3), 17 (ORMDL3/GSDMB), and 22 (IL2RB) correlated with asthma." (PMID 32512817, 2020). "We uncovered several promising tissue-specific regulatory TFs or genes for Alzheimer’s disease (e.g. ZIC1 and STX1B) and asthma (e.g. CSF3 and IL1RL1)." (PMID 29378629, 2018). "We uncovered several promising tissue-specific regulatory TFs or genes for AD (e.g. ZIC1 and STX1B) and asthma (e.g. CSF3 and IL1RL1) in our case studies." (PMID 29378629, 2018). "This was confirmed in an animal model where introduction of soluble IL1RL1 decreased pro-inflammatory cytokine (IL4, IL5 and IL13) production in a murine asthma model after treatment with IL33." (PMID 21629437, 2010). "Additionally, there was a report of an animal study showing that mice deficient in IL1RL1 showed attenuated airway inflammation after challenge with an allergen, suggesting that IL1RL1 isoform B might be participating in the excessive inflammation observed in asthma." (PMID 21629437, 2010). "For instance, SNPs in IL1RL1 (rs1420101) and IL4RA (rs8832) are linked to enhanced responses to asthma biologics, particularly anti-IL-5 drugs, independent of other clinical factors." (PMID 40004611, 2025). "IL‐33 mRNA expression was not elevated in asthma whereas the expression of mRNA for IL1RL1, the IL‐33 receptor, was up‐regulated in the sputum of severe eosinophilic asthma." (PMID 35986608, 2023). "The meta-analysis identified as the 5 most significant loci on chromosomes 17q12-21 near PGAP3 and ERBB2, 6p21.32 near HLA-122 DRB1/-DQA1, 5q22.1 near TSLP, 2q12 near IL1RL1/IL18R, and 9p24.1 near IL33 in both the whole sample and in the subset that included only subjects with early-onset asthma." (PMID 33673725, 2021). "However, homozygote carriers of the asthma risk allele in Signal C (rs17027258; AA) also presented elevated levels of soluble IL1RL1 protein following HDM stimulation, suggesting potential roles of circulating soluble IL1RL1 that may induce asthma under certain conditions." (PMID 32324168, 2020). "Asthma is a disease with demonstrated heritability in humans, and several genes, including the IKZF3-ZPBP2-GSDMB-ORMDL3 locus, HLA-DQ, IL1RL1, IL33, TSLP, SLC22A5, SMAD3, and RORA have been consistently associated with asthma in genome-wide association studies (GWAS)." (PMID 23984888, 2013).
asthma (continued). "High IL1RL1-a production in the airways of children with severe RSV bronchiolitis suggests this molecule plays a role in modifying the inflammatory response to epithelial damage, as it does in severe asthma." (PMID 22574108, 2012). "By inference, an increased role for the IL33/IL1RL1 signalling pathway may be present due to the increased abundance and therefore signalling response to these isoforms in some but not all asthma patients." (PMID 39301832, 2024). "However, OS biomarkers NO2−, lipid peroxide, protein sulfhydrils, and inflammatory biomarkers TNFα, IL-4, IL-37, IL-1β, IL-1RL1, IL-1R1, NLRP3, and TGF-β1 showed positive association with asthma in nonsmokers, but not in smokers." (PMID 37367073, 2023). "However, there was no considerable link between serum IL1RL1-a protein levels and methylation degree or asthma pathogenesis." (PMID 33781317, 2021). "We hypothesize that the genetic heterogeneity of the IL1RL1 locus may be partly due to inducible eQTLs that affect gene transcription in asthma patients but not in healthy controls." (PMID 32324168, 2020). "Therefore, we investigated the effect of asthma-relevant stimulations of cultured HBECs obtained from asthma subjects on IL1RL1 expression in carriers and noncarriers of phenotype-associated alleles (i.e., inducible eQTLs)." (PMID 32324168, 2020). "Furthermore, we found no deletions or duplications nominally associated with asthma symptoms in loci consistently associated with the disease in previous studies, including: DENND1B, IL1RL1, PDE4D, TSLP, IL13, HLA-DR/DQ and IL33 regions." (PMID 30262839, 2018). "A severe asthma GWAS identified a novel locus, CDHR3, that had not been observed using broader asthma definitions, in addition to the known asthma susceptibility loci GSDMB, IL33, and IL1RL1." (PMID 28774304, 2017). "Thus, the asthma loci IL33, IL1RL1/IL18R1, RORA, and IL13 previously identified by GWAS belong to the same pathway, and could modify airway inflammation and interleukin responses that are crucial for the development of asthma." (PMID 23565190, 2013). "IL1RL1 and IL1RAP mRNA expression was not differentiated amongst asthma cohorts in blood but IL1RL1 was elevated in the sputum of severe eosinophilic asthma." (PMID 35986608, 2023). "A very recent GWA study of severe asthma in Europeans found strong evidence for two previously established loci (ORMDL3/GSDMB and IL1RL1/IL18R1) in patients with severe asthma but did not identify any novel loci." (PMID 23028483, 2012).
allergic disease (16 papers, 2010 to 2024). An immune response that occurs following re-exposure to an innocuous antigen, and that requires the presence of existing antibodies against that antigen. "Genetic studies have shown significant associations between IL1RL1 and IL33 genetic variants and allergic diseases such as asthma, atopic dermatitis and EoE in humans." (PMID 39654685, 2024). "Genome-wide association studies (GWAS) have shown an association between allergic diseases and genetic polymorphisms in genes such as TSLP, IL33, and IL1RL1, which encode the IL-33 receptor ST2." (PMID 36941691, 2023). "IL‐33‐ST2 (IL‐1RL1 ) axis has been regarded as one of the key players also in allergic diseases, asthma and atopic dermatitis." (PMID 33133517, 2020). "Especially, IL-33-ST2 (IL-1RL1) axis has been regarded as the villain in allergic diseases such as asthma and atopic dermatitis and in autoimmune diseases such as rheumatoid arthritis." (PMID 30233590, 2018). "Furthermore, a two-sample MR approach leveraging large GWAS and eQTL databases suggested a potential causal role for IL4, IL1RL1, RP11-13A1.1, FCER1A and MS4A2, RUNX1, and ACLS6 expression in various allergic diseases and serum IgE levels." (PMID 36725846, 2023). "However, the role of Blimp‐1 in follicular Tregs may be context‐dependent, as Blimp‐1 expression induces an ST2+ (Il1rl1, IL‐33R) allergy‐promoting phenotype of Tregs in the house dust mite model of allergic asthma." (PMID 32799350, 2020). "Indeed, the connection between allergy and Interleukin 1 receptor-like-1 (IL1R1) is already known." (PMID 25477900, 2014).
heart failure (12 papers, 2014 to 2024). Inability of the heart to pump blood at an adequate rate to meet tissue metabolic requirements. "Circulating levels of soluble interleukin 1 receptor-like 1 (sST2) are increased in heart failure and associated with poor outcome, likely because of the activation of inflammation and fibrosis." (PMID 32664340, 2020). "Note that soluble sST2 that is a biomarker for heart failure is also known as interleukin-1 receptor-like 1 (IL1RL1 GeneID: 9173)." (PMID 36937911, 2023). "IL-1RL1, in particular, is also a prognostic factor for heart failure (HF) and myocardial infarction (MI), forming a bridge between Th2 activation/allergy sensitization and CVD." (PMID 32849633, 2020). "AS of the IL1RL1 gene encoding interleukin-1 receptor-like 1 or ST2 protein produces two forms of the protein, a transmembrane (ST2L) form and a soluble form (sST2), the levels of which are elevated in serum of CVD patients with heart failure or MI." (PMID 25988147, 2014).
atopic dermatitis (11 papers, 2009 to 2025). "A SNP in the distal promoter region of IL1RL1, rs6543116 (-26999G/A), was associated with increased risk for atopic dermatitis and up-regulation of gene expression." (PMID 21629437, 2010). "A functional promoter polymorphism (rs6543116) in the IL1RL1 gene was previously associated with atopic dermatitis and high total IgE levels in the sera from the same patients." (PMID 19852851, 2009). "Interestingly, polymorphisms in the HRH4 gene were found to be associated with atopic dermatitis, while variants of the IL1RL1 gene have been associated with atopic dermatitis and atopic asthma." (PMID 27421833, 2016). "Quantitative analysis revealed that the expression of NMB, IL2RA, IL1RL1, and PRKCQ was markedly elevated in individuals with atopic dermatitis relative to healthy controls (p < 0.05 or p < 0.01), indicating their possible involvement in disease development." (PMID 41346997, 2025).
eosinophilia (11 papers, 2012 to 2024). "SNPs in the IL1RL1 gene have previously been shown to affect serum level of eosinophilia and IgE in other models." (PMID 22723975, 2012). "IL1RL1 is the receptor for interleukin‐33 (IL‐33) which acts as a selective chemoattractant of Th2 cells, and elicits IL5‐dependent eosinophilia." (PMID 33295083, 2021). "IL1RL1, a membrane receptor whose expression is continuously upregulated during the progression of T2D, can bind to IL-33 to activate the TH2 inflammatory response and eosinophilia." (PMID 36248223, 2022).
breast cancer (9 papers, 2013 to 2024). A primary or metastatic malignant neoplasm involving the breast. "Compared to wild-type (WT) controls, Il1rl1-deficiency led to delayed tumorigenesis in mice tested in the syngeneic 4T1 breast cancer model." (PMID 28119694, 2016). "Furthermore, there were fewer MDSCs in tumor lesions of Il1rl1-deficient mice, while treatment with exogenous IL-33 promoted the accumulation of these suppressor cells in mammary tumors." (PMID 28119694, 2016). "As for the protective factors (IL1RL1, TXNIP, and APP), IL1RL1 was similarly identified to function as a tumor suppressor in mammary tumor." (PMID 32328125, 2020). "Well-designed tissue comparison assays showed an elevated IL-33 and IL1RL1 or ST2 in tissue of both human breast cancer and non-small-cell-lung cancer (NSCLC), compared to adjacent non-tumor tissues." (PMID 30619376, 2018). "Indeed, NK cells showed increased IFN-γ production in Il1rl1−/− mice injected with 4T1 breast cancer cells, which translated into improved antitumor immunity." (PMID 28119694, 2016).
COVID-19 (8 papers, 2021 to 2025). A disease caused by infection with severe acute respiratory syndrome coronavirus 2. "We also detected increased mRNA levels of soluble interleukin-1 receptor-like 1 (sIL1-RL1) and transforming growth factor β1 (TGF-β1) in the left ventricular myocardium of deceased COVID-19 patients." (PMID 34745111, 2021).
Arthritis (7 papers, 2010 to 2024). Inflammation of a joint. "In a mouse model of methylated bovine serum albumin (mBSA)-induced arthritis, suppression of IL-33R (IL1RL1) expression in neutrophils could prevent IL-33-mediated neutrophil migration into the knee joint." (PMID 32719716, 2020). "The treatment of mice with a soluble IL1RL1-Ig Fc fusion protein as decoy receptor or with a blocking anti-IL1RL1 antibody resulted in a reduction of the collagen induced arthritis and of the inflammatory response in the lung proving the therapeutic potential of the IL-33 and IL1RL1 interaction." (PMID 24503933, 2014). "Although there is good evidence for a role of IL33/IL1RL1 in human and experimental arthritis, no SNPs in these genes were found associated with susceptibility to RA in GWAS data." (PMID 21629437, 2010).
atherosclerosis (6 papers, 2013 to 2024). A disease characterized by the build-up of fatty material and calcium deposition in the arterial wall resulting in partial or complete occlusion of the arterial lumen. "Although IL-33/IL1RL1 interaction has been suggested to be important in the development of atherosclerosis, genetic influences of the polymorphisms of IL33 in human ischemic stroke are unclear." (PMID 24107076, 2013). "Taking into account all these considerations, in the present study we aimed to determine, for the first time, whether 6 genetic variants at IL33 and IL1RL1, previously associated with immune-mediated diseases, are involved in the risk of subclinical atherosclerosis in Spanish patients with RA." (PMID 26571131, 2015).
autoimmune disease (6 papers, 2010 to 2024). A disorder resulting from loss of function or tissue destruction of an organ or multiple organs, arising from humoral or cellular immune responses of the individual to their own tissue constituents. "IL1RL1 and closely linked genes have been implicated in an array of autoimmune diseases." (PMID 21629437, 2010). "IL1RL1 activates the MyD88/NF-κB signaling pathway to promote the suppressive effect of Tregs in inflammatory diseases, but the role of IL-33 in autoimmune diseases and tumors is controversial." (PMID 34012433, 2021). "Taken together, the evidence suggests a pro-inflammatory role for IL1RL1 and IL18R1 in autoimmune disease." (PMID 32719716, 2020).
childhood asthma (6 papers, 2012 to 2022). "Five genes were found to be associated with self-reported childhood asthma in COPDGene: IL1RL1, IL13, LINC01149, near GSDMB, and in the C11orf30-LRRC32 region." (PMID 30373671, 2018). "IL1RL1 gene cluster polymorphisms and SNPs such as rs3771166, rs1420101 and rs1041973 have been associated with childhood asthma." (PMID 22574108, 2012). "Prior GWAS have implicated genetic susceptibility specific to childhood asthma, including variants in ORMDL3/GSDMB, IL1RL1, IL33, and RAD50." (PMID 30373671, 2018). "There is increasing evidence, from both clinical and genetic studies, that IL1RL1 plays an important role in the development of childhood asthma." (PMID 22574108, 2012). "Interestingly, polymorphisms in the IL33 gene or in the IL-33 receptor (IL1RL1), coding for ST2, are associated with childhood asthma and blood eosinophil count." (PMID 35392216, 2022).
inflammatory bowel disease (6 papers, 2010 to 2024). A spectrum of small and large bowel inflammatory diseases of unknown etiology. "For instance, genetic ablation of IL1RL1 protected mice from developing experimental inflammatory bowel disease, and an antagonist of IL1RL1 could reduce the symptoms of colitis in these animals." (PMID 32719716, 2020). "Recent evidence suggests that the IL-33/IL1RL1 axis plays a critical role in several autoimmune and inflammatory disorders; however, its mechanistic role in inflammatory bowel disease (IBD) has not been clearly defined." (PMID 23634226, 2013). "The IL1RL1/IL33 signaling axis was implicated in inflammatory bowel disease (IBD) for the first time in two recent studies characterizing IL1RL1 and IL33 protein and mRNA expression in IBD patients." (PMID 21629437, 2010).
lung carcinoma (6 papers, 2016 to 2025). "The association between IL1RL1 variants and lung cancer risk was assessed using logistic regression to calculate odds ratios (ORs) and 95% confidence intervals (CIs)." (PMID 37719702, 2023). "In this study, we explore the association betweewn IL1RL1 polymorphisms and lung cancer susceptibility in the Chinese Han population." (PMID 37719702, 2023). "This study is the first to explore IL1RL1 polymorphisms (rs12479210, rs3771180, rs1420101, rs3771175, rs10208293, and rs10197862) and lung cancer susceptibility in the Chinese Han population." (PMID 37719702, 2023). "In conclusion, this study suggests that IL1RL1 genetic variants (rs12479210 and rs1420101) contribute to the susceptibility to lung cancer in the Chinese Han population." (PMID 37719702, 2023). "The results showed that rs12479210 and rs1420101 in IL1RL1 were associated with an increased risk of lung cancer in the Chinese Han population." (PMID 37719702, 2023). "This study reports for the first time a significant correlation between IL1RL1 polymorphisms (rs12479210 and rs1420101) and risk of lung cancer in the Chinese Han population." (PMID 37719702, 2023). "First, the significance of IL1RL1 polymorphisms and lung cancer susceptibility was only performed in the Chinese Han population." (PMID 37719702, 2023). "In this study, we aimed to explore the association between IL1RL1 genetic polymorphisms and lung cancer risk in the Chinese Han population." (PMID 37719702, 2023). "Consistent with previous evidence, interleukin-33 (IL33) and interleukin 1 receptor-like 1 (IL1RL1) were found to be increased in lung cancer and associated with disease clinical stage." (PMID 33005178, 2020). "However, there are few studies on the correlation between IL1RL1 polymorphisms and lung cancer susceptibility." (PMID 37719702, 2023). "These genetic variants of IL1RL1 may provide new biomarkers for early diagnosis of lung cancer, and it helps us to have a deeper understanding of the pathogenesis of lung cancer." (PMID 37719702, 2023). "Finally, the specific molecular mechanism of IL1RL1 genetic variants in the occurrence and development of lung cancer risk is unclear." (PMID 37719702, 2023). "However, further research is needed to confirm these findings and to better understand the molecular mechanisms underlying the association between IL1RL1 polymorphisms and lung cancer risk." (PMID 37719702, 2023). "Therefore, in future research, we will collect more comprehensive data, including BMI and alcohol consumption, lung cancer subtypes, etc., to better evaluate the association between IL1RL1 polymorphisms and lung cancer risk." (PMID 37719702, 2023). "Therefore, in this study we aimed to assess the possible association between six IL1RL1 gene polymorphisms (rs12479210, rs3771180, rs1420101, rs3771175, rs10208293, and rs10197862) and susceptibility to lung cancer in the Chinese Han population." (PMID 37719702, 2023). "Therefore, we speculateed that these two SNPs (rs12479210 and rs1420101) may affect the risk of lung cancer by regulating the expression of IL1RL1." (PMID 37719702, 2023). "However, little is known about the correlation between IL1RL1 polymorphisms and lung cancer." (PMID 37719702, 2023). "We found statistically significant differences between six SNPs in IL1RL1 and the expression level of IL1RL1 in lung cancer tissues using GTEx Portal database (p < 0.001)." (PMID 37719702, 2023). "The expression level of the IL1RL1 gene is lower in lung cancer tissue than normal tissue, and there are significant differences in the expression levels of IL1RL1 between rs12479210 and rs1420101 genetypes in lung cancer tissue (p < 0.05)." (PMID 37719702, 2023). "Bioinformatics analysis results revealed that there were significant differences between rs12479210 and rs1420101 and the expression level of IL1RL1 in lung cancer tissue." (PMID 37719702, 2023).